PRAF2 (PRA1 domain family member 2)
Description:
May be involved in ER/Golgi transport and vesicular traffic. Plays a proapoptotic role in cerulenin-induced neuroblastoma apoptosis.
Synonyms: JM4; Yip6a
Tractability: Antibody: UniProt places it where antibodies can reach, with high confidence; UniProt predicts a signal peptide or a membrane-spanning region. PROTAC: ubiquitination databases record sites on it; its protein half-life has been measured.
Gene: Protein-coding gene on chromosome X (49,071,161 to 49,074,017, reverse strand). Ensembl gene ENSG00000243279.
Subcellular location: Endosome membrane
Subcellular location (Human Protein Atlas): Endoplasmic reticulum; Vesicles
Gene Ontology:
Molecular function: protein binding
Biological process: L-glutamate transmembrane transport
Cellular component: membrane; endosome membrane; GABA-ergic synapse; glutamatergic synapse; postsynapse; presynapse
Homologues: Orthologues: macaque PRAF2 (98% identical), dog PRAF2 (94% identical), rat Praf2 (92% identical), mouse Praf2 (91% identical), guinea pig PRAF2 (90% identical), rabbit PRAF2 (86% identical), zebrafish praf2 (58% identical), Drosophila melanogaster Jwa (39% identical), Caenorhabditis elegans praf-3 (31% identical). Paralogues in human: ARL6IP5 (46% identical).
Diseases named in the same sentence as PRAF2 in open-access papers:
PRAF2 is named in the same sentence as 17 diseases in open-access papers, as found by Europe PMC text mining. Sharing a sentence is not in itself a finding about the gene and the disease. The quoted sentences say what the papers report.
hepatocellular carcinoma (3 papers, 2019). A malignant tumor that arises from hepatocytes. "In contrast to paired normal tissue samples, PRAF2 is observed to be overexpressed in tumor tissue samples of hepatocellular carcinoma and malignant glioma." (PMID 31649487, 2019). "It has been reported that overexpression of PRAF2 shows a significantly correlation with malignant clinical characteristics and predicts poor prognostic outcome in malignant glioma, neuroblastoma and hepatocellular carcinoma." (PMID 31200670, 2019).
malignant glioma (2 papers, 2019). A grade III or grade IV glioma arising from the central nervous system. "In molecular mechanism, monomeric/dimeric state of PRAF2 may influence its subcellular localization and distribution that leads to functional differences in malignant glioma cells." (PMID 31200670, 2019).
neuroblastoma (2 papers, 2019). Neuroblastoma (NB) is the most common solid, extracranial childhood tumor. "A study of Yco has shown that PRAF2 accelerates cell migration and proliferation and predicts poor prognosis in neuroblastoma." (PMID 31649487, 2019).
breast carcinoma (1 paper, 2010). "The decrease in caspase activation observed after Praf2 RNAi was not apoptotic stimulus-specific nor cell type-specific, as it was evident also in U2OS cells treated with paclitaxel or doxorubicin and in the breast cancer cell line MDA-MB 231 treated with etoposide." (PMID 21203533, 2010).
cocaine addicts (1 paper, 2013).
colon cancer (1 paper, 2019). "Our experimental results reveal for the first time that PRAF2 overexpression could increase the secretion of colon cancer cell exosomes, and promote the migration and invasion of tumor cells in a JAG2-dependent manner through signal transduction in the microenvironment." (PMID 31198409, 2019).
colorectal cancer (1 paper, 2019). A primary or metastatic malignant neoplasm that affects the colon or rectum. "This is the evidence supporting the biological function of JAG2 through non-canonical Notch and non-EMT-dependent pathways and also the first demonstration of the functions of PRAF2 in colorectal cancer cells." (PMID 31198409, 2019). "When JAG2 was overexpressed in colorectal cancer cell line HT29, PRAF2 was up-regulated, then the number of exosomes secreted by colorectal cancer cells was significantly increased and the level of JAG2 and PRAF2 proteins in exosomes was upregulated." (PMID 31198409, 2019). "JAG2-rich exosomes were released from colorectal cancer cells in a PRAF2-dependent way, while these exosomes regulated the metastasis of colorectal cancer cells in a paracrine manner." (PMID 31198409, 2019). "Further analysis revealed the co-expression of JAG2 with PRAF2 in colorectal cancer cells." (PMID 31198409, 2019).
melanoma (1 paper, 2023). A malignant, usually aggressive tumor composed of atypical, neoplastic melanocytes. "Associations with the presence of TERT promoter mutations revealed an overlap of 30 genes in the three bulk RNA-seq cohorts (in melanoma and across entities), of which six genes were consistently up- or down-regulated (up: ARL17A, FBF1, KAZALD1, PRAF2; down: PLEKHB2, RASGRP3)." (PMID 37418389, 2023).
osteosarcoma (1 paper, 2010). A usually aggressive malignant bone-forming mesenchymal neoplasm, predominantly affecting adolescents and young adults. "On the same track, reducing Praf2 expression by RNAi in the U2OS osteosarcoma cell line, we observed an increased resistance to cytotoxic effect of the chemotherapeutic drug etoposide." (PMID 21203533, 2010). "The osteosarcoma cell line U2OS expresses relatively high levels of Praf2." (PMID 21203533, 2010).
ovarian tumor (1 paper, 2019). "Also, PRAF2 is overexpressed in breast, colon, lung, and ovarian tumor tissue specimens relative to normal tissue specimens." (PMID 31198409, 2019).
squamous cell carcinoma (1 paper, 2019). A carcinoma arising from squamous epithelial cells. "In present study, we first used TCGA data of ESCC patients via the UALCAN data portal and found that the PRAF2 were up-expressed in squamous cell carcinoma but not in adenocarcinoma tissues compared to normal tissues (P = 0.027)." (PMID 31200670, 2019).
tumor (5 papers, 2010 to 2019). "PRAF2 mRNA expression was remarkable increased in ESCC samples compared with associated non-tumor tissues." (PMID 31200670, 2019). "Our study has confirmed that high PRAF2 expression was associated with lower tumor differentiation grade and later TNM stage in ESCC." (PMID 31200670, 2019). "The PRAF2 mRNA expression was significantly increased in ESCC tissues compared with matched surrounding non-tumor tissues." (PMID 31200670, 2019). "Now, PRAF2 has been considered as oncogene since it is highly expressed in multiple tumor tissues of the breast, colon, lung and ovary cancer." (PMID 31200670, 2019). "Then, we collected the cancer and matched associated non-tumor from ESCC patients and tested the PRAF2 mRNA expression by qPCR method." (PMID 31200670, 2019). "And how to reconcile these data with the observation that the expression of Praf2 in human tumor tissues is higher than in normal tissues of the same patient?" (PMID 21203533, 2010). "Moreover, PRAF2 may play important roles in the malignant transformation of above tumor types." (PMID 31200670, 2019). "The possibility that Praf2, forming a complex with RTN proteins could be able to potentiate the anti-apoptotic activity of Bcl-2/xL, as shown for RTN3, could also help to explain why an increased Praf2 expression would be selected during tumor formation." (PMID 21203533, 2010). "Unlike the PRAF2, PRAF1, another member of PRA family, is known as a potential inhibitory factor of tumor cell invasion by regulating the MAPK and integrin αvβ3 pathways." (PMID 31200670, 2019).
cancer (4 papers, 2010 to 2023). A tumor composed of atypical neoplastic, often pleomorphic cells that invade other tissues. "One gene (PRAF2) showed a consistent up-regulation also in the cell line data comprising other cancer entities (CCLE cohort)." (PMID 37418389, 2023). "Prenylated Rab acceptor 1 domain family, member 2 (PRAF2) is involved in the occurrence and progression of several malignant tumors." (PMID 31200670, 2019). "Through consulting literature, only PRAF2 is closely related to the progress of cancer." (PMID 31649487, 2019). "PRAF2 mRNA expression was markedly elevated in cancer tissues compared with non-cancerous normal tissues." (PMID 31200670, 2019). "Previous study shows PRAF2 interacts with the CCR5 and thereby contributes to cancer cell migration, which may partially explain the mechanism of metastasis." (PMID 31200670, 2019).
PRAF2 also shares sentences with these, for which no sentence is quoted: adenocarcinoma (1 paper); cutaneous squamous cell carcinoma (1); esophageal squamous cell carcinoma (1); gastric cancer (1).